RNU2-7P (RNA, U2 small nuclear 7, pseudogene)
Gene: Small nuclear RNA gene on chromosome 13 (20,612,161 to 20,612,338, forward strand). Ensembl gene ENSG00000222726.
Homologues: Orthologues: chimpanzee U2 (98% identical), pig U2 (82% identical), mouse Gm25202 (81% identical), guinea pig U2 (70% identical), rabbit U2 (28% identical), rabbit U2 (22% identical). Paralogues in human: U2 (85% identical), RNU2-3P (84% identical), RNU2-2 (81% identical), RNU2-25P (81% identical), U2 (80% identical), RNU2-4P (79% identical), RNU2-48P (78% identical), RNU2-52P (78% identical), RNU2-17P (78% identical), RNU2-37P (78% identical), RNU2-57P (77% identical), RNU2-26P (76% identical), and 66 more.